LINC01063 (long independently transcribed non-coding RNA 1063)
Gene: Long non-coding RNA gene on chromosome 3 (196,631,009 to 196,632,706, reverse strand). Ensembl gene ENSG00000232065.
Diseases named in the same sentence as LINC01063 in open-access papers:
LINC01063 is named in the same sentence as 7 diseases in open-access papers, as found by Europe PMC text mining. Sharing a sentence is not in itself a finding about the gene and the disease. The quoted sentences say what the papers report.
colon cancer (2 papers, 2020 to 2022). "The survival analysis showed that a high expression of AC008760.1, AC009237.14, AC083809.1, AL391422.4, AL445645.1, LINC01063, LINC01234, and LINC02381 was associated with a poor prognosis in colon cancer." (PMID 32425969, 2020). "The GEPIA database showed that AC008760.1, AC009237.14, AC083809.1, AL391422.4, AL445645.1, LINC01063, and LINC01234 were highly expressed in colon cancer and that AC016027.1 has low expression in colon cancer." (PMID 32425969, 2020). "A total of 709 autophagy-related genes were identified in colon cancer tissues, and 11 autophagy-related lncRNAs (AL138756.1, LINC01063, CD27-AS1, LINC00957, EIF3J-DT, LINC02474, SNHG16, AC105219.1, AC068580.3, LINC02381, and LINC01011) were finally selected and set as prognosis-related lncRNAs." (PMID 36035142, 2022).
colorectal tumor (1 paper, 2025). "Furthermore, LINC01063 has been identified as an oncogene in melanoma and an autophagy-associated lncRNA capable of predicting colorectal tumor prognosis, while LINC01518 has been shown to function as an endogenous competing RNA in esophageal squamous cell carcinoma." (PMID 40496210, 2025).
tumor (3 papers, 2023 to 2024). "Lastly, LINC01063 has been implicated in various tumor cell processes, including proliferation, migration, invasion, and epithelial–mesenchymal transition (EMT)." (PMID 38907744, 2024). "SLC25A30AS1 and LINC01063 are only shown to be constituent factors in the tumour prognosis model, but their specific role in tumours has not been studied." (PMID 36844873, 2023).
cancer (2 papers, 2021 to 2022). A tumor composed of atypical neoplastic, often pleomorphic cells that invade other tissues. "Among the 11 autophagy-related lncRNAs, 8 lncRNAs were already verified to be associated with cancer development: LINC01063, CD27-AS1, LINC00957, EIF3J-DT, LINC02474, SNHG16, LINC02381, and LINC01011." (PMID 36035142, 2022). "Some of the irlncRNAs previously associated with the malignant phenotypes of various cancers, including MIAT, TYMSOS, LINC01063, HOXC-AS1, LINC02454, SCAT1, and LINC01322 were identified in the process of modeling in this study." (PMID 34167440, 2021).
LINC01063 also shares sentences with these, for which no sentence is quoted: esophageal squamous cell carcinoma (1 paper); liver cancer (1); melanoma (1).